TSHR (thyroid stimulating hormone receptor)
Diseases named in the same sentence as TSHR in open-access papers (continued):
Sharing a sentence is not in itself a finding about the gene and the disease.
Graves disease (continued). "Constitutively activating TSHR mutations may also occur as germline mutations and in the situation cause hereditary non-autoimmune hyperthyroidism that is transmitted in an autosomal dominant manner." (PMID 32303903, 2020). "Thyrotropin receptor (TSHR) autoantibodies (TRAbs) are a hallmark of Graves’ disease (GD)." (PMID 29435670, 2018). "Association studies of thyroid-stimulating hormone receptor (TSHR) gene with Graves’ disease risk." (PMID 28421036, 2017). "Autoimmune thyroid disease (AITD) comprises diseases including Hashimoto's thyroiditis and Graves' disease, both characterized by reactivity to autoantigens causing, respectively, inflammatory destruction and autoimmune stimulation of the thyroid-stimulating hormone receptor." (PMID 25127106, 2014). "Autoimmune reactions towards TSHR (strong support) cause Graves disease (OMIM ID 275000)." (PMID 23950964, 2013). "Furthermore, there appear to be disease-specific genes, such as the gene encoding the TSHR in Graves' disease and a larger group of susceptibility genes, such as CTLA4, which are common to many autoimmune diseases." (PMID 22530160, 2012). "Constitutively activating mutations (CAMs) of the TSHR result in non-autoimmune hyperthyroidism." (PMID 21835055, 2011). "However, an important feature of alemtuzumab‐associated Graves’ disease is that it often fluctuates from hyperthyroidism to hypothyroidism and vice versa, in relation to the prevailing activities of stimulatory and blocking TSHR‐Ab." (PMID 35604323, 2022). "Graves’ disease (GD) is the most common cause of hyperthyroidism, in which patients develop an anti-thyroid autoimmune response, including lymphocytic infiltration and the presence of autoantibodies against thyroglobulin, thyroid peroxidase and the thyroid-stimulating hormone receptor (TSHR)." (PMID 32485674, 2020). "In sum, constitutive activation of the cAMP cascade, predominantly via TSHR mutations, is the molecular hallmark of thyroid autonomy in its various presentation as solitary toxic adenoma, toxic multinodular goitre or even hereditary non-autoimmune hyperthyroidism." (PMID 32303903, 2020). "For example, Graves disease plus a functioning nodule with a TSHR mutation may cause more apparent hyperthyroidism, while Hashimoto thyroiditis may mask the hyperthyroidism caused by the nodule harboring a gain-of-function TSHR mutation." (PMID 30319546, 2018). "Nevertheless, inhibitors of VEGF‐A–VEGFR2 signaling could reduce the sizes of thyroid goiter, thus providing a novel therapeutic concept of targeting vasculatures in these TSHR‐associated diseases such as Graves' disease and warranting further clinical investigation." (PMID 28438786, 2017). "Targeting the thyroid-stimulating hormone receptor (TSHR) constitutes a novel therapeutic strategy for Graves’ disease (GD), an AID driven by thyroid receptor antibodies (TRAb)." (PMID 41357209, 2025). "GO results from an autoimmune condition, Graves’ disease, where antibodies attack the thyroid-stimulating hormone receptor (TSH-R) and induce hyperthyroidism." (PMID 40572742, 2025). "Graves’ disease (GD) is an organ-specific autoimmune disorder characterized by the presence of thyroid-stimulating hormone receptor autoantibodies (TRAb), leading to hyperthyroidism." (PMID 41035651, 2025). "Graves’ disease is primarily mediated by thyroid-stimulating immunoglobulins (TSAbs), which bind to and activate the thyroid-stimulating hormone receptor (TSHR)." (PMID 40772166, 2025). "In both patients, the laboratory workup revealed negative autoantibodies for thyroglobulin (TGAb), anti-thyroid peroxidase (TPOAb) and thyroid-stimulating hormone receptor (TSHRAb), excluding Graves’ disease or thyrotoxicosis by autoimmune thyroiditis." (PMID 39565383, 2025). "Graves’ disease (GD) is an autoimmune disease that occurs in response to the development of autoantibodies against the TSH receptor (TSHR)." (PMID 40622195, 2025).
Graves disease (continued). "Graves’ disease (GD) is a common autoimmune disorder of the thyroid gland characterised by the continuous activation of the thyroid stimulating hormone receptor (TSHR) by autoantibodies, leading to hyperthyroidism." (PMID 40093006, 2025). "In Graves’ disease, the primary autoantibodies target the thyroid stimulating hormone receptor (TSHR) on thyroid cells." (PMID 40416990, 2025). "In Graves’ Disease (GD), pathogenesis is centered around autoreactive B cells which are specific for thyroid stimulating hormone receptor (TSHR)." (PMID 40264771, 2025). "Graves' disease is an autoimmune disease, whereby antibodies target and hyperstimulate the thyroid-stimulating hormone receptor (TSHR) on the thyroid gland." (PMID 40693095, 2025). "Graves’ disease (GD) is a common autoimmune disorder characterized by hyperthyroidism resulting from thyroid-stimulating hormone receptor (TSHR)-activating autoantibodies." (PMID 41306435, 2025). "Graves' disease is an autoimmune disorder in which the thyroid gland becomes overactive due to the action of TSHR-specific conformation-dependent autoantibodies." (PMID 40224487, 2025). "In this case, elevated thyroid-stimulating immunoglobulin and the presence of thyroid-stimulating hormone receptor antibodies confirmed the diagnosis of Graves’ disease." (PMID 41189855, 2025). "In autoimmune thyroid diseases like Graves’ disease and Hashimoto’s thyroiditis, anti-TSHR antibodies (TSHR-Ab) are core pathological factors, modulating TSHR activity and leading to hyperthyroidism or hypothyroidism." (PMID 40837371, 2025). "The thyroid-stimulating hormone receptor (TSHR) gene has also been evaluated in AIT, although it is primarily associated with Graves’ disease and Graves’ orbitopathy." (PMID 40650076, 2025). "In Graves’ disease, the autoreactive immune response targets the TSHR, leading to the production of TRAb." (PMID 41415293, 2025). "When patients are affected by Graves’ hyperthyroidism, the TSHR-specific T cells and the presence of TSHR autoantibodies can result in extrathyroidal problems including PTM and GO." (PMID 41157173, 2025). "The most prominent biomarker for Graves’ disease is the presence of autoantibodies targeting the thyroid-stimulating hormone receptor (TSHR)." (PMID 38475046, 2024). "Thyroid-specific genes are seen as interesting candidates, including primarily TPO and Tg genes in the case of AIT and TSHR genes in Graves’ disease (GD)." (PMID 38542286, 2024). "Loss of immune tolerance to the thyroid-stimulating hormone receptor (TSHR) and generation of activating antibodies against the protein are central to the thyroidal pathology of Graves disease." (PMID 38752390, 2024). "The presence of TSHR-Ab is reported in the most recent guidelines as a distinctive marker of AIT1 in the form of amiodarone-induced Graves’ disease, but this point probably needs to be revised in future guidelines." (PMID 37731073, 2024). "Seven years before, after severe stress, she had Graves’ disease with elevated plasma levels of TSHR-Ab." (PMID 38813368, 2024). "A functional assay demonstrated that only TSHR-Ab obtained from patients displaying AIT1 and Graves’ disease features stimulated the TSH receptor, whereas TSHR-Ab obtained from AIT2 patients displayed a neutral or inhibiting activity." (PMID 37731073, 2024). "The current theories regarding TAO pathogenesis center around autoimmunity against thyroid-stimulating hormone receptor (TSHR), which is commonly recognized as the cause of Graves’ disease but is also expressed in orbital tissues." (PMID 38564194, 2024). "Graves’ Disease is marked by the presence of thyroid-stimulating hormone receptor (TSHR) antibodies, which are capable of stimulating the TSHR, leading to overproduction of thyroid hormones and hyperthyroidism." (PMID 39776440, 2024). "Graves’ disease is an auto-immune disease caused by a certain type of TSH Receptor Antibodies (TRAb), which binds and stimulates TSHR." (PMID 37233673, 2023).
Graves disease (continued). "In the late TSHR-immunized group, 50% developed a mild-moderate autoimmune hyperthyroidism, 10% a severe hyperthyroidism, and 40% of the animals had a normal thyroid morphology." (PMID 37435490, 2023). "Although studies have reported that GD patients have all three types of TSHR autoantibodies, stimulating antibodies constitute the distinguishing characteristic of Grave’s hyperthyroidism." (PMID 37859983, 2023). "Treatment of the early TSHR-immunized mice with linsitinib improved the disease and only 11.1% of the mice showed a mild-moderate autoimmune hyperthyroidism, whereas 88.9% showed a normal thyroid function." (PMID 37435490, 2023). "Graves' disease (GD) is a thyroid-specific autoimmune disorder primarily attributed to the breakdown of tolerance to the thyroid-stimulating hormone receptor." (PMID 38003622, 2023). "This understanding of the mechanism of action of K1-70TM is helpful in developing applications for its use in controlling activation of the TSHR in Graves’ disease, in Graves’ orbitopathy and in thyroid cancer." (PMID 36069797, 2023). "For almost 40 years, the presence of antibodies to TSHR have been used to differentiate Graves’ disease, and this approach is constantly being improved." (PMID 37047169, 2023). "TSHR-stimulating autoantibodies bind to the TSHR at a similar extracellular site as the thyroid stimulating hormone (TSH) itself and cause deregulated TSHR hyper-activation resulting in Graves’ disease." (PMID 37082124, 2023). "Assessment of the titer and pattern of autoantibodies to TSHR is widely used to differentiate Graves’ disease from toxic multinodular goitre type A and other forms of thyrotoxicosis." (PMID 37047169, 2023). "The ability of NCGC00229600 to suppress TSHR activity in retroorbital fibroblasts is important in terms of preventing ophthalmopathy, the most severe symptom of Graves’ disease." (PMID 37047169, 2023). "Treatment with linsitinib in the early TSHR-immunized group prevented the development of autoimmune hyperthyroidism." (PMID 37435490, 2023). "In summary, we investigated the development of Graves’ Disease and thyroid eye disease in a murine mouse model after immunization with the A-subunit of the TSHR." (PMID 37810891, 2023). "ATX-GD-59 (a combination of two TSHR peptides) was evaluated in a phase 1 study of 12 patients with previously untreated mild-to-moderate Graves’ hyperthyroidism, receiving 10 doses of ATX-GD-59 intradermally over an 18-week period." (PMID 38202079, 2023). "The ability of blocking autoantibodies to prevent TSHR hyperactivation can be used to treat Graves’ disease and Graves’ orbitopathy." (PMID 37047169, 2023). "Autoimmune thyroid diseases are found in an average of 5% of the population, the most common among which is diffuse toxic goiter (Graves’ disease), which develops as a result of an autoimmune attack to TSHR." (PMID 37047169, 2023). "NCGC00229600 also prevented TSH- and antibody-dependent AC stimulation in a primary culture of fibroblasts obtained from the retroorbital region of patients with Graves’ disease and was characterized by increased TSHR expression." (PMID 37047169, 2023). "Inappropriate mutational activation of the thyroid stimulating hormone receptor (TSHR) beyond its native basal activity can lead to Grave’s disease." (PMID 37687205, 2023). "In the early TSHR-immunized group 80% developed an autoimmune hyperthyroidism, with 40% having a mild-moderate thyroid dysfunction and 40% a severe thyroid dysfunction, while 20% of the early TSHR- control group remained a normal/subclinical thyroid function." (PMID 37435490, 2023). "The thyroid of the fetus of a mother with Graves’ disease (GD) is affected by the transplacental passage of both antithyroid drugs (ATDs) and thyroid-stimulating hormone receptor antibodies (TRAb)." (PMID 35565939, 2022).
Graves disease (continued). "Using sensitive bioassays, stimulatory TSHR‐Ab are found in almost all patients with Graves’ disease, but circulating levels are threefold higher in GO patients, with a strong correlation with GO activity and severity." (PMID 35604323, 2022). "During her stay, she was diagnosed with Graves' disease by hormone profile and thyroid-stimulating hormone receptor (TSH-R) antibody positivity." (PMID 35547433, 2022). "In clinical practice, TSHR antibodies in hypothyroid patients can also be detected by routine TSH binding inhibition assays, as employed in Graves’ disease, but are likely to be mostly TSHR blocking antibodies." (PMID 35909553, 2022). "One major message from these studies is that we cannot easily and reliably detect TSHR blocking antibodies in patients with Graves’ disease using currently available techniques and bioassays." (PMID 35909553, 2022). "A large literature shows that the vast majority of patients with new onset and untreated Graves’ disease have detectable TSHR-Abs (over 90%) making their measurement a useful clinical diagnostic tool." (PMID 35909553, 2022). "The problem remains that it is difficult to detect TSHR blocking antibodies in patients with Graves’ disease since their affinity for the TSHR must be greater than the stimulating antibodies causing the hyperthyroidism." (PMID 35909553, 2022). "In contrast, autoimmune hyperthyroidism, that is Graves’ disease, is characterised by autoreactive B cells secreting autoantibodies against the TSH receptor (TSHR)." (PMID 35175936, 2022). "The interest in the TSHR has been largely fueled by its role as a major human autoantigen in autoimmune thyroid disease, especially Graves’ disease." (PMID 36305581, 2022). "Autoantibodies against thyroid peroxidase (TPO) and thyroglobulin (TG), which characterize Hashimoto’s thyroiditis (HT), and thyroid-stimulating receptors (TSHR), a marker for Graves’ disease (GD), were used in this study." (PMID 36002642, 2022). "Background and Aims: Stimulation of the TSH receptor (TSHR) by TSHR autoantibodies (TRAb) has a key role in the pathogenesis of Graves’ disease (GD) and Graves’ orbitopathy (GO)." (PMID 35869534, 2022). "Yet, the direct pathogenic potential of these autoantibodies has not been clearly demonstrated, except for thyroid stimulating antibodies that target the TSHR in Graves’ disease." (PMID 35572553, 2022). "Grave’s disease is an organ-specific autoimmune disorder in which the binding of the autoantibodies to the thyroid-stimulating hormone receptor (TSHR) increases thyroid function leading to hyperthyroidism." (PMID 35495619, 2022). "Pathophysiologic indicators in Graves’ disease include anti-thyroid stimulating hormone receptor antibodies (TRAb)." (PMID 35846322, 2022). "The logic behind this data shows that blocking TSHR antibodies cannot possibly be reliably detected in a TSH bioassay of serum from patients with Graves’ disease which contain a strong stimulating TSHR antibody." (PMID 35909553, 2022). "Thyroid function tests revealed a biochemically hyperthyroid state with elevated anti-thyroid peroxidase antibodies and thyroid stimulating hormone receptor antibodies, findings consistent with Graves' disease." (PMID 36420235, 2022). "Graves' disease (GD) is a form of hyperthyroidism due to thyroid-stimulating hormone receptor autoantibodies (TRAb), and anti-thyroid peroxidase antibodies (anti-TPO antibodies)." (PMID 36514581, 2022). "The TSHR-ddH2O mouse group (Z-score > 0) can be clearly separated from βgal mouse group (Z-score 0) concerning autoimmune hyperthyroidism (P ≤ 0.0001) and orbitopathy (P ≤ 0.0001)." (PMID 33593429, 2021). "GO develops mainly in the context of an autoimmune condition, Graves disease, in which thyrotropin receptor (TSHR) activation by thyroid-stimulating antibodies mimics the action of TSH, producing hyperthyroidism." (PMID 34473251, 2021).
Graves disease (continued). "Graves’ disease (GD) is an autoimmune disorder in which stimulatory autoantibodies activate thyroid stimulating hormone receptors (TSHR), leading to excessive amounts of thyroid hormones." (PMID 34026662, 2021). "In Graves’ disease, there are three thyroid-stimulating hormone receptor (TSHR) antibodies with different functions (stimulation, blocking, and cleavage)." (PMID 33737640, 2021). "In Graves’ disease, natural aAb to the TSH-receptor (TSHR-aAb) are causative for the clinical phenotype, as they bind as endocrine active agonists to the TSH-receptor and stimulate hyperthyroidism and thyroid eye disease." (PMID 34884891, 2021). "It is therefore conceivable that the FSHR and the LHR represent disease-relevant autoantigens in human subjects, as the TSHR does in Graves’ disease." (PMID 34948471, 2021). "Graves’ disease (GD) is an organ-specific autoimmune disease that arises due to the breakthrough of tolerance to thyroid stimulating hormone receptor (TSHR)." (PMID 33912135, 2021). "TSHR activation occurs not only at elevated TSH but also in Graves’ disease when thyroid-stimulating autoantibodies (TSAb) activate TSHR on orbital fibroblasts and T cells." (PMID 34574358, 2021). "Graves’ disease is a form of hyperthyroidism characterized by the presence of thyroid-stimulating hormone receptor (TSHR) autoantibodies, which mimic the effects of thyroid stimulating hormone (TSH)." (PMID 34044861, 2021). "In patients with Graves’ disease, the anti-TSHR autoantibodies overactivate the TSH pathway, resulting into hyperthyroidism." (PMID 34916298, 2021). "In Graves’ disease, TSHR enhances adipogenesis not only in orbital adipose tissue but also in white adipose tissue." (PMID 34574358, 2021). "Human TSHR was expressed as a fusion protein with luciferase, allowing a highly sensitive and reliable assay for the diagnosis of TSHR-aAb in Graves’ disease." (PMID 34948471, 2021). "The excess thyroid hormone secretion that characterises Graves’ disease (GD) is generated when stimulatory antibodies bind to the thyroid stimulating hormone receptor on the follicular cell of the thyroid gland." (PMID 34289872, 2021). "Thyroid stimulating hormone receptor (TSHR) released by EV improves autoantibody-mediated activation of Graves disease by blocking autoantibodies." (PMID 34239366, 2021). "The differently treated TSHR-immunized mouse groups developed autoimmune hyperthyroidism or orbitopathy to varying degrees." (PMID 33593429, 2021). "Graves' disease (GD) is a common autoimmune disease in which stimulatory autoantibodies bind to the thyroid-stimulating hormone receptor (TSHR), resulting in increased thyroid gland activity and growth." (PMID 33542676, 2021). "Graves’ disease is characterized by the presence of antithyroid antibodies against the TSH receptor (TSHR), which activate downstream pathways, thus mimicking activation by TSH." (PMID 34916298, 2021). "Elevated circulating thyroid hormones in Graves’ hyperthyroidism arise because of stimulating TSHR autoantibodies (TRAbs), which bind to leucine-rich repeats in the extracellular domain of the TSHR located on the surface of the thyrocytes." (PMID 32845332, 2020). "Graves’ disease (GD) is a thyroid-specific autoimmune disease that thyroid-stimulating antibody (TSAb) stimulates thyroid-stimulating hormone receptor (TSHR) and leads to overproduction of thyroid hormones." (PMID 32555990, 2020). "These early observations indicate that blocking TSHR activity in vivo with K1-70 has promising applications in controlling stimulation of the receptor in Graves’ disease, GO and in thyroid cancer." (PMID 32472423, 2020). "Once it had been demonstrated that stimulation of the TSHR by autoantibodies in patients’ sera has a central role in the pathogenesis of Graves’ disease measurement of TRAb for diagnosis and monitoring of patients has become increasingly important." (PMID 32472423, 2020).